SPCS2 (signal peptidase complex subunit 2)
Description:
Component of the signal peptidase complex (SPC) which catalyzes the cleavage of N-terminal signal sequences from nascent proteins as they are translocated into the lumen of the endoplasmic reticulum. Enhances the enzymatic activity of SPC and facilitates the interactions between different components of the translocation site (By similarity).
Synonyms: KIAA0102
Tractability: Antibody: UniProt predicts a signal peptide or a membrane-spanning region. PROTAC: ubiquitination databases record sites on it; its protein half-life has been measured.
Gene: Protein-coding gene on chromosome 11 (74,949,259 to 74,979,033, forward strand). Ensembl gene ENSG00000118363.
Subcellular location: Endoplasmic reticulum membrane
Subcellular location (Human Protein Atlas): Vesicles
Pathways (Reactome):
Metabolism of proteins: SRP-dependent cotranslational protein targeting to membrane; Synthesis, secretion, and deacylation of Ghrelin; Synthesis, secretion, and inactivation of Glucagon-like Peptide-1 (GLP-1); Synthesis, secretion, and inactivation of Glucose-dependent Insulinotropic Polypeptide (GIP)
Disease: Maturation of DENV proteins; Maturation of hRSV A proteins
Cell-Cell communication: Regulation of CDH1 posttranslational processing and trafficking to plasma membrane
Gene Ontology:
Molecular function: protein binding
Biological process: protein processing; protein targeting to ER
Cellular component: endoplasmic reticulum membrane; signal peptidase complex; membrane
Genetic constraint (gnomAD): Loss-of-function variants: 2 observed, 16.17 expected, observed/expected ratio (o/e) 0.12, 90% interval 0.05 to 0.39. The upper end of that interval is the gene's LOEUF score, 0.39, which puts it in group 1 of 6, group 1 being the genes least tolerant of losing a copy. Missense variants: 140 observed, 214.24 expected, observed/expected ratio (o/e) 0.65, 90% interval 0.57 to 0.75. Synonymous variants: 54 observed, 73.05 expected, observed/expected ratio (o/e) 0.74, 90% interval 0.59 to 0.93.
Homologues: Orthologues: chimpanzee SPCS2 (99% identical), mouse Spcs2 (96% identical), dog SPCS2 (95% identical), rat Spcs2 (95% identical), rabbit SPCS2 (95% identical), guinea pig SPCS2 (93% identical), pig SPCS2 (90% identical), tropical clawed frog spcs2 (75% identical), zebrafish spcs2 (64% identical), Drosophila melanogaster Spase25 (35% identical), Caenorhabditis elegans spcs-2 (33% identical).
Diseases named in the same sentence as SPCS2 in open-access papers:
SPCS2 is named in the same sentence as 12 diseases in open-access papers, as found by Europe PMC text mining. Sharing a sentence is not in itself a finding about the gene and the disease. The quoted sentences say what the papers report.
viral infection (2 papers, 2013 to 2018). "It seemed that knockdown of SPCS1 had a higher impact on the later stage of viral infection compared to either SPCS2 or SPCS3, which are possibly involved in the catalytic activity of the signal peptidase." (PMID 24009510, 2013). "Using a cutoff of greater than 30% increase in viral infection normalized to cell viability in two independent screens, we identified HSPA5, TMED2, SPCS2, and DDIT3 as factors whose overexpression increased DENV infection, indicating rate limitation associated with these important proviral factors." (PMID 29451494, 2018).
head and neck squamous cell carcinoma (1 paper, 2022). A squamous cell carcinoma that arises from any of the following anatomic sites: lip and oral cavity, nasal cavity, paranasal sinuses, pharynx, larynx, and salivary glands. "In the current study, we aimed to investigate the expression of the five microsomal signal peptidase complex (SPC) subunit genes (SEC11A, SEC11C, SPCS1, SPCS2, and SPCS3) in head and neck squamous cell carcinoma (HNSC) and to explore their prognostic value." (PMID 35653344, 2022).
hepatocellular carcinoma (1 paper, 2022). A malignant tumor that arises from hepatocytes. "SPCS2 has a significant diagnostic value for hepatocellular carcinoma (HCC)." (PMID 35653344, 2022).
cancer (1 paper, 2021). A tumor composed of atypical neoplastic, often pleomorphic cells that invade other tissues. "Among these, TMA7 (Translation Machinery Associated 7 Homolog) and SPCS2 (Signal Peptidase Complex Subunit 2) reached the highest levels of diagnostic accuracy in our study, but their role in cancer is still unknown." (PMID 33925480, 2021). "The same analysis conducted on TMA7, SPCS2, CDCP1, NT5C3A and SRP54 revealed a homogeneous expression in the majority of 33 TCGA histotypes of cancer." (PMID 33925480, 2021).
tumor (1 paper, 2022). "Results showed that SEC11A, SPCS2 and SPCS3 were significantly upregulated in the tumor group than in the normal group." (PMID 35653344, 2022).
SPCS2 also shares sentences with these, for which no sentence is quoted: diabetes (1 paper); glioblastoma (1); Insulin resistance (1); leukemia (1); melanoma (1); parathyroid adenoma (1); Type 2 Diabetes (1).